PDE9A (phosphodiesterase 9A)
Description:
Specifically hydrolyzes the second messenger cGMP, which is a key regulator of many important physiological processes. Highly specific: compared to other members of the cyclic nucleotide phosphodiesterase family, has the highest affinity and selectivity for cGMP. Specifically regulates natriuretic-peptide-dependent cGMP signaling in heart, acting as a regulator of cardiac hypertrophy in myocytes and muscle. Does not regulate nitric oxide-dependent cGMP in heart. Additional experiments are required to confirm whether its ability to hydrolyze natriuretic-peptide-dependent cGMP is specific to heart or is a general feature of the protein (Probable). In brain, involved in cognitive function, such as learning and long-term memory (By similarity).
Synonyms: HSPDE9A2
Tractability: Small molecule: an approved drug acts on it; a structure with a bound ligand is known; a high-quality ligand is known; it has a high-quality binding pocket; it belongs to a druggable protein family. Antibody: UniProt places it where antibodies can reach, with high confidence; its Gene Ontology location is reachable by antibodies, with high confidence; the Human Protein Atlas places it where antibodies can reach. PROTAC: ubiquitination databases record sites on it; a small molecule that binds it is known.
Target class: Enzyme; Phosphodiesterase; Phosphodiesterase 9; Phosphodiesterase 9A
Chemical probes: BAY-7081 (high quality), PF-4181366 (high quality), Tovinontrine
Gene: Protein-coding gene on chromosome 21 (42,653,591 to 42,775,513, forward strand). Ensembl gene ENSG00000160191.
Subcellular location: Cell projection, ruffle membrane (Isoform PDE9A1); Cytoplasm, perinuclear region; Golgi apparatus; Endoplasmic reticulum; Cell membrane, sarcolemma; Cell projection, ruffle membrane (Isoform PDE9A2); Cytoplasm (Isoform PDE9A3); Cytoplasm (Isoform PDE9A17)
Subcellular location (Human Protein Atlas): Cytosol; Nucleoplasm; Plasma membrane
Pathways (Reactome):
Hemostasis: cGMP effects
Gene Ontology:
Molecular function: 3',5'-cyclic-GMP phosphodiesterase activity; protein binding; 3',5'-cyclic-AMP phosphodiesterase activity; 3',5'-cyclic-nucleotide phosphodiesterase activity; phosphoric diester hydrolase activity
Biological process: cGMP catabolic process; cGMP metabolic process; negative regulation of cAMP/PKA signal transduction; positive regulation of cardiac muscle hypertrophy; signal transduction; negative regulation of neural precursor cell proliferation; positive regulation of long-term synaptic potentiation
Cellular component: cytoplasm; cytosol; endoplasmic reticulum; Golgi apparatus; plasma membrane; sarcolemma; perikaryon; perinuclear region of cytoplasm; ruffle membrane
Genetic constraint (gnomAD): Loss-of-function variants: 33 observed, 40.4 expected, observed/expected ratio (o/e) 0.82, 90% interval 0.62 to 1.09. The upper end of that interval is the gene's LOEUF score, 1.09, which puts it in group 4 of 6, group 1 being the genes least tolerant of losing a copy. Missense variants: 428 observed, 506.81 expected, observed/expected ratio (o/e) 0.84, 90% interval 0.78 to 0.92. Synonymous variants: 180 observed, 193.33 expected, observed/expected ratio (o/e) 0.93, 90% interval 0.82 to 1.05.
Homologues: Orthologues: chimpanzee PDE9A (99% identical), macaque PDE9A (98% identical), dog PDE9A (83% identical), mouse Pde9a (83% identical), rat Pde9a (82% identical), guinea pig PDE9A (82% identical), pig PDE9A (82% identical), zebrafish pde9aa (67% identical), tropical clawed frog pde9a (56% identical). Paralogues in human: PDE5A (22% identical), PDE11A (22% identical), PDE2A (22% identical), PDE8A (22% identical), PDE8B (22% identical), PDE6A (21% identical), PDE4C (20% identical), PDE6B (20% identical), PDE10A (20% identical), PDE4D (20% identical), PDE4B (20% identical), PDE6C (20% identical), and 8 more.
Diseases named in the same sentence as PDE9A in open-access papers:
PDE9A is named in the same sentence as 67 diseases in open-access papers, as found by Europe PMC text mining. Sharing a sentence is not in itself a finding about the gene and the disease. The quoted sentences say what the papers report.
Alzheimer disease (8 papers, 2016 to 2025). A progressive, neurodegenerative disease characterized by loss of function and death of nerve cells in several areas of the brain leading to loss of cognitive function such as memory and language. "Bay 73-6691, an inaugural phosphodiesterase inhibitor selective for the PDE9A subtype, has previously been employed in studies to ameliorate memory deficits and cognitive impairments in Alzheimer’s disease." (PMID 39806097, 2025). "Nonetheless, among these proteins, PDE9A is a druggable-target, which is currently in clinical trials for Alzheimer’s disease, while FPRs have been postulated as possible targets for mitigating ischemia-induced inflammation." (PMID 33589590, 2021). "Such investigations take on added significance in light of the fact that high quality PDE9A inhibitors are now available and have entered into initial clinical trials to explore procognitive efficacy in Alzheimer’s disease and schizophrenia." (PMID 31507355, 2019). "Based on these finding, PDE9A inhibitors have been advanced into initial clinical studies to assess the potential to improve cognitive function in patients with Alzheimer’s disease and schizophrenia." (PMID 31507355, 2019). "Discovery of novel PDE9A inhibitors with antioxidant activities for treatment of Alzheimer’s disease." (PMID 29363360, 2018). "Indeed, PDE9A inhibitors are under evaluation in clinical trials as a treatment for Alzheimer’s disease and schizophrenia." (PMID 31507355, 2019).
cardiac hypertrophy (5 papers, 2021 to 2025). "In the TAC model of HF, PDE9A deficiency ameliorates cardiac hypertrophy and ventricular function." (PMID 37971403, 2024). "These discoveries revealed that PDE9A controls a nitric oxide-independent cGMP pathway in the heart and can drive cardiac hypertrophy when overactive." (PMID 40650137, 2025). "In one study, chronic PDE9A inhibitor therapy not only attenuated cardiac hypertrophy, but also significantly reduced interstitial fibrosis and collagen gene expression in pressure-overloaded hearts." (PMID 40650137, 2025). "PDE9A is expressed in hearts from mice and humans and is upregulated in myocardial hypertrophy and HF." (PMID 37971403, 2024). "In a murine model of chronic LV pressure overload, NP‐dependent cGMP‐PKG signaling attenuated myocardial hypertrophy and reversed LV dysfunction when PDE9A was inhibited." (PMID 34569183, 2021). "Notably, PDE9A expression is low at baseline in the myocardium, but is upregulated in cardiac hypertrophy and failure." (PMID 40650137, 2025). "Although expression is low in the myocardium, it is worth noting that in the PDE family, PDE9 may have the highest affinity for cGMP, especially in cardiovascular disease, where PDE9A expression is upregulated by cardiac hypertrophy and HF." (PMID 36081943, 2022). "Similarly, an independent group demonstrated that a novel PDE9A inhibitor (compound C33(S)) protected rats against isoproterenol-induced cardiac hypertrophy, with treated animals displaying smaller increases in heart mass and less fibrosis compared to controls." (PMID 40650137, 2025). "Thus, PDE9A inhibitors may have greater effectiveness than PDE5A inhibitors for treating cardiac hypertrophy when NO production is low." (PMID 37971403, 2024). "Studies of left ventricular (LV) disease first revealed this phenomenon: failing human hearts and animal models of hypertrophy show robust upregulation of PDE9A mRNA and protein compared to non-failing controls." (PMID 40650137, 2025). "Unlike PDE5A, PDE9A inhibition can reverse preestablished cardiac hypertrophy independent of NOS activity." (PMID 37971403, 2024).
Cognitive impairment (5 papers, 2016 to 2025). Abnormal cognition is characterized by deficits in thinking, reasoning, or remembering. "PDE9A is a cGMP-specific phosphodiesterase expressed in neurons throughout the brain that has attracted attention as a therapeutic target to treat cognitive disorders." (PMID 31507355, 2019). "Thus PDE9A overexpression in DS could be an exacerbating influence both for cognitive deficits in DS, as well as for AD in DS." (PMID 29215943, 2018).
breast carcinoma (4 papers, 2013 to 2025). "In oncological contexts, elevated PDE9A expression has been observed in malignant breast tumors compared to normal tissues." (PMID 41179677, 2025). "PDE9A is also the main regulator of basal cyclic guanosine monophosphate (cGMP) levels in human breast cancer cells." (PMID 31221986, 2019). "PDE9A inhibitor has been reported to induce apoptosis of breast cancer cell lines through caspase 3 activation." (PMID 23544068, 2013). "Treatment of MCF-7 and MDA-MB468 breast cancer cells with BAY 73–6691 led to a dose- and time-dependent reduction in cell proliferation and an increase in apoptosis, highlighting PDE9A as a promising therapeutic target in breast cancer." (PMID 41179677, 2025).
heart failure (4 papers, 2018 to 2025). Inability of the heart to pump blood at an adequate rate to meet tissue metabolic requirements. "Notably, PDE9A levels are especially elevated in hearts from patients with heart failure with preserved ejection fraction (HFpEF), suggesting a strong association between natriuretic peptide-driven signaling and PDE9A upregulation." (PMID 40650137, 2025). "In addition, various PDE family members, PDE1A, PDE3A, PDE4B, PDE4D, PDE5 and PDE9A, are implicated in the cardiac stress response, which triggers pathological cardiac remodeling and ultimately cardiac dysfunction (e.g., heart failure and arrhythmias)." (PMID 29461511, 2018). "This specialization means that when NO synthesis is reduced—as occurs in many forms of heart failure—PDE9A becomes the dominant regulator of cGMP in cardiomyocytes." (PMID 40650137, 2025). "Early-phase clinical studies in heart failure populations suggest that PDE9A inhibitors are well tolerated and effectively augment cGMP levels, although dedicated trials in RHF are still needed." (PMID 40650137, 2025). "The recognition of PDE9A as a contributor to maladaptive remodeling has spurred investigations into PDE9A inhibition as a therapeutic strategy for heart failure." (PMID 40650137, 2025). "PDE9A expression was identified in human and rodent hearts, where its expression increased upon hypertrophy and heart failure development." (PMID 29461511, 2018). "With focused clinical efforts and mechanistic insight, PDE9A inhibitors could become a valuable tool in improving outcomes for patients with this often-overlooked form of heart failure." (PMID 40650137, 2025). "Similarly, in isoproterenol-induced heart failure models, PDE9A inhibition increased PLB phosphorylation and improved calcium reuptake via SERCA2a." (PMID 40650137, 2025). "PDE9A is expressed in cardiomyocytes and further upregulated by hypertrophy and heart failure." (PMID 29766323, 2018). "The authors proposed that PDE9A as an alternative therapeutic approach which might be effective alone or in combination with other drugs for treatment of heart failure." (PMID 29766323, 2018). "For instance, in models of heart failure with preserved ejection fraction (HFpEF)—which often involves pulmonary hypertension and RHF—chronic PDE9A inhibitor treatment improved diastolic function." (PMID 40650137, 2025). "Phosphodiesterase 9A (PDE9A), a cGMP-specific phosphodiesterase, has been proposed as a potential contributor to RHF pathogenesis by suppressing the cardioprotective cGMP–PKG signaling pathway—a conclusion largely extrapolated from left-sided heart failure models." (PMID 40650137, 2025). "Upregulation of PDE9A in cardiac (and cognitive) diseases is of great interest, since it was first shown that PDE9 regulates NP-derived cGMP pools, and thus it may even be a more potent contributor to heart failure pathology than PDE5." (PMID 30249014, 2018).
schizophrenia (3 papers, 2019 to 2022). A major psychotic disorder characterized by abnormalities in the perception or expression of reality. "The potent, selective phosphodiesterase-9A inhibitor BI 409306 may be beneficial for patients with attenuated psychosis syndrome and could prevent relapse in patients with schizophrenia." (PMID 35089373, 2022). "BI 409306, a potent and selective PDE9A inhibitor that may improve NMDA signalling, is currently under clinical development as a potential treatment for APS and for prevention of relapse in schizophrenia." (PMID 35089373, 2022).
colorectal cancer (2 papers, 2021 to 2022). A primary or metastatic malignant neoplasm that affects the colon or rectum. "The major contribution of pVHL is to suppress clear-cell renal cell carcinoma in kidney cancer and phosphodiesterase 9A gene as novel biomarker in human colorectal cancer." (PMID 35399005, 2022). "The study presented here was designed to carry out the prognostic value as a biomarker of PDE9A in Colorectal cancer (CRC)." (PMID 34016083, 2021). "PDE9A expression was downregulated in various colorectal cancer types including Colorectal Adenoma, Colon Mucinous Adenocarcinoma, Colon Adenocarcinoma, Colon Adenoma, Colon Carcinoma, Colorectal Carcinoma, etc.." (PMID 34016083, 2021).
Hypertension (2 papers, 2025). The presence of chronic increased pressure in the systemic arterial system. "More recently, in an HFpEF-like model combining obesity, hypertension, and mild pressure overload, chronic PDE9A inhibition similarly reduced myocardial collagen deposition by ~60% and suppressed pro-fibrotic gene expression." (PMID 40650137, 2025).
leukemia (2 papers, 2020 to 2021). A malignant (clonal) hematologic disorder, involving hematopoietic stem cells and characterized by the presence of primitive or atypical myeloid or lymphoid cells in the bone marrow and the blood. "On hematological diseases cellular model, healthy hematopoietic stem progenitor cells overexpressed the leukemia stem cell-specific genes LY86, LRG1, and PDE9A under the induction of leukemia microvesicles." (PMID 35095520, 2021). "Moreover, healthy hematopoietic stem progenitor cells (HSPCs) can be transformed genetically by leukemia macrovesicles to over express LSC specific genes, which contains LY86, LRG1 and PDE9A and so on." (PMID 33604283, 2020).
lung carcinoma (2 papers, 2013 to 2017). "With regard to PDE9A, the level of mRNA expression was not necessarily low and was not always restored by 5-aza-dC treatment in any of the cell lines examined, indicating that DNA methylation is not the only mechanism responsible for PDE9A regulation in lung cancers." (PMID 23544068, 2013).
acute lymphoblastic leukemia (1 paper, 2013). Leukemia with an acute onset, characterized by the presence of lymphoblasts in the bone marrow and the peripheral blood. "On the other hand, breakpoints within the PDE9A gene have been frequently observed in B-cell precursor acute lymphoblastic leukemia." (PMID 23544068, 2013).
adrenal tumor (1 paper, 2020). "Transcriptome profiling of pediatric ACTs (n = 16) and normal adrenal cortex samples (n = 6) revealed that PDE2A, PDE6D, PDE8A, and PDE9A are highly expressed in both normal and adrenal tumor tissue, compared to other PDE family members." (PMID 32098292, 2020).
anorexia nervosa (1 paper, 2023). A disorder most often seen in adolescent females characterized by a refusal to maintain a minimally normal body weight, an intense fear of gaining weight, a disturbance in body image, and, in postmenarcheal females, the development of amenorrhea. "Furthermore, psychiatric disorders also had some causal effects on PDEs [obsessive–compulsive disorder on increased PDE6D and decreased PDE2A and PDE4D; anorexia nervosa on decreased PDE9A]." (PMID 37605207, 2023).
aortic stenosis (1 paper, 2025). Aortic valve stenosis is a aortic valve disease caused by the incomplete opening of the aortic valve. "In human specimens, hearts from patients with dilated cardiomyopathy or aortic stenosis also exhibit significantly higher PDE9A protein expression and enzymatic activity compared to non-failing hearts." (PMID 40650137, 2025).
Ataxia (1 paper, 2025). Ataxia refers to impaired coordination of voluntary muscle movement. "To investigate the possible role of PDE9A in CHIP-associated ataxia, we tested whether PDE9A serves as a ubiquitination substrate for CHIP." (PMID 39806097, 2025). "In a preclinical rodent model of CHIP-related ataxia, we observed that CHIP mutations lead to increased levels of phosphodiesterase 9A (PDE9A), whose role in this context remains poorly understood." (PMID 39806097, 2025). "Here, we investigated the molecular mechanisms underlying the role of PDE9A in CHIP-related ataxia and demonstrated that CHIP binds to PDE9A, facilitating its polyubiquitination and autophagic degradation." (PMID 39806097, 2025). "Thus, PDE9A upregulation considerably exacerbates ataxia associated with CHIP mutations, and targeting the interaction between PDE9A and CHIP is an innovative therapeutic strategy for CHIP-related ataxia." (PMID 39806097, 2025). "Here, CHIP mutations are found to disrupt degradation of phosphodiesterase PDE9A, with the CHIP-PDE9A interaction representing a potential therapeutic target for restoring cerebellar neuronal function and preventing degeneration in CHIP-related ataxia." (PMID 39806097, 2025).
atherosclerosis (1 paper, 2018). A disease characterized by the build-up of fatty material and calcium deposition in the arterial wall resulting in partial or complete occlusion of the arterial lumen. "Here, we showed that cardiac PDE9A is upregulated even in an early stage of atherosclerosis-induced cardiac dysfunction." (PMID 30249014, 2018). "As upregulated PDE9A limits the elevation of cGMP levels and blocks cardioprotective PKG signaling, it may be a favorable drug target in atherosclerosis-associated cardiac dysfunction." (PMID 30249014, 2018).
autism (1 paper, 2016). Persistent deficits in social interaction and communication and interaction as well as a markedly restricted repertoire of activity and interest as well as repetitive patterns of behavior. "Our data suggest that PDE9A inhibitors may additionally be considered for treating DMD-associated autism as well as other cerebellum defined subsets of ASD." (PMID 27676442, 2016).
Breast Invasive Carcinoma (1 paper, 2021). "Of importance, lower expression levels of the PDE9A, Iqca1, Sirpb1b, CD244, SP140, and PIP5k1b genes was found in the BC patients with unfavorable prognosis in terms of 5-year survival analysis (dataset of Breast Invasive Carcinoma [n = 1075] from TCGA)." (PMID 33426510, 2021).
colitis (1 paper, 2021). Inflammation of the colon. "This study reports that a selective inhibitor of PDE9A, PF-04447943 protects colon against DSS-induced colitis for the first time." (PMID 33967779, 2021).